CCND1 (cyclin D1)
Diseases named in the same sentence as CCND1 in open-access papers (continued):
Sharing a sentence is not in itself a finding about the gene and the disease.
myeloma (continued). "We and others showed that super-enhancers were associated to key genes contributing to myeloma pathogenesis, such as MYC, IRF4, CCND1, NSD2 and MAF39,66." (PMID 35198065, 2022). "Knockdown of miR-551b caused increased TTP, led to less Cyclin D1 and E2F1 level, resulting in decreased myeloma proliferation and enhanced Dex sensitivity." (PMID 34983615, 2022). "Screening of multiple myeloma (MM) cell lines for sensitivity to venetoclax showed that high sensitivity was restricted to cell lines with CCND1 translocations." (PMID 36261486, 2022). "This translocation cause IGH/CCND1 fusion and transcriptional activation of CCND1 oncogene by the IGH promoter/enhancer sequences, which contribute to multiple myeloma biology." (PMID 36119749, 2022). "One of the striking features of myeloma biology is the early observation that a dichotomous over-expression of the cell cycle regulators CCND1 and CCND2 overarches genetic diversification." (PMID 34521827, 2021). "Significantly lower progression-free and overall survival were observed in cyclin D1-positive multiple myeloma patients." (PMID 33923996, 2021). "CLL malignant B cells express significantly higher CCND2 than CCND1 levels and as in CCND2high myeloma PC, we found that the same CCND2 super-enhancer is active in CLL B cells." (PMID 34521827, 2021). "CLCN3 also accelerates the G0/G1 to S phase transition in the cell cycle by enhancing the phosphorylation of ERK1/2 and upregulating cyclin E and cyclin D1 in multiple myeloma cells." (PMID 31608175, 2019). "Critical early events include immunoglobulin translocations with MMSET and CCND1, hyperdiploidy and complex structural variation processes hitting key myeloma genes." (PMID 31444325, 2019). "We validated this correlation between gain(1q)-HRD and CCND2 and gain(11q25)-HRD and CCND1 expression in the Myeloma IX dataset." (PMID 28584253, 2018). "Similar to MCL, in multiple myeloma, cyclin D1 overexpression is also frequently observed and the disease is responding well to proteasomal inhibition." (PMID 30180865, 2018). "A recently published preclinical study also demonstrated a link between cyclin D1 expression and bortezomib sensitivity in multiple myeloma cell lines." (PMID 30180865, 2018). "We therefore included, for comparison, the U266 multiple myeloma (MM) cell line, in which CCND1 is activated by the insertion of an enhancer element." (PMID 29066743, 2017). "Although the translocation breakpoints along chromosome arm 11q13 lie within 47 kb and 300 kb centromeric to CCND1, the classified breakpoints characteristic of multiple myelomas are scattered within this upstream region." (PMID 25799187, 2015). "We probed the CCND1 locus in the human H929 multiple myeloma cell line using 3C and subsequently detected two loops at 220 kb and 330 kb in the upstream flanking region." (PMID 25799187, 2015). "One particular breakpoint in multiple myeloma lies 300 kb upstream of the CCND1 locus, between the promoter and the base of one of the loops mapped above." (PMID 25799187, 2015). "HDACi has been shown to induce deregulation of cell cycle genes, cyclin D1 and Cdk4 leading to hypophosphorylation of pRb, thereby resulting in cell cycle arrest in multiple myeloma cells." (PMID 24586690, 2014). "Increased expression of thisfactor results in increasing growth and survivalof myeloma cells, their attachment to bone marrowstromal cells, tumor formation and VEGFsecretion through targeting CCND1, integrin β7,and CCR1 (chemokine receptor) genes." (PMID 24567933, 2014).
myeloma (continued). "Ilimaquinone and ethylsmenoquinone repressed the expression of cyclin D1, c-myc, and axin-2, which are β-catenin/T-cell factor-dependent genes, and inhibited the proliferation of multiple myeloma cells." (PMID 24879546, 2014). "Cyclin D1 expression is found in a subset of plasma cell myelomas, especially those with lymphoplasmacytic morphology." (PMID 24349805, 2013). "Gene expression profiling of B cells from M-protein-positive p80HT mice revealed aberrant expression of genes known to be important in the pathogenesis of multiple myeloma, including cyclin D1, cyclin D2, Blimp1, survivin, IL-10 and IL-15." (PMID 22642622, 2012). "Cyclin D1 was the dominant proteinin the immature myeloma cells, whereas p16 was primarilyexpressed in normal plasma cells and mature myelomacells." (PMID 24744619, 2012). "Multiple myeloma (MM) patients with cyclin D1 overexpression showed reduced CD56 expression and increased circulating tumor cells (CTC) levels, suggesting that cyclin D1 may contribute to MM cell dissemination capacity." (PMID 40674249, 2025). "Specifically, our study highlights novel functions of cyclin D1 in cell adhesion and morphology of myeloma cells, which may influence their dissemination capacity." (PMID 40674249, 2025). "This is consistent with the favorable prognosis in the myeloma subgroup with the IGH/CCND1 fusion gene, implying the venetoclax might be beneficial for high-risk patients with elevated CCND1 expression." (PMID 38278930, 2024). "Similarly, the amplification of Cyclin D1 in multiple myeloma was related to the expression of multidrug resistance." (PMID 37814227, 2023). "The key myeloma-initiating genetic events are hyperdiploidy and translocations involving the immunoglobulin heavy chain (IgH) enhancer on chromosome 14, which leads to the activation of oncogenes (e.g., CCND1, CCND3, MAF, and MMSET)." (PMID 35982976, 2022). "As CCND1 that encodes for cyclin D1 has been proven to be a direct target of miR-340-5p by luciferase assay, our data of methylation-mediated silencing of miR-340-5p may account for the overexpression of CCND1 in myeloma." (PMID 31064412, 2019). "Similarly with DTX3L, cyclin D1 expression increased myeloma adhesion to stromal cells and fibronectin." (PMID 29765356, 2018). "Thus, the decrease in p21, increase in Cyclin D1, and increase in Rb phosphorylation all indicate that Reelin facilitates myeloma cell proliferation by regulating key proteins involved in G1/S transition." (PMID 28345605, 2017). "We report here the characterization of new biological functions of cyclin D1 in myeloma cells." (PMID 27286258, 2016). "Over-expression of CCND1, the gene that codes for cyclin D1, one of the three isoforms of cyclin D, is found in over 80% of MM cases, making this cyclin a favored target for anti-myeloma drug development." (PMID 27655636, 2016). "Furthermore, it has been reported that cyproheptadine altered cyclin D1 expression in myeloma and leukemia." (PMID 25886177, 2015). "Based on prior molecular evaluations of secondary myeloma and the disparity in cyclin D1 expression between the 2 tumors, we contend that the 2 tumors are more likely to have been clonally distinct; more extensive molecular evaluation of the tumors would be required to establish this definitively." (PMID 24715915, 2014). "Genetically, myeloma is characterized by universal upregulation of cyclin D1, D2 or D3." (PMID 24330858, 2013). "Likewise, myeloma cells treated with 20 μM orlistat exhibited a significant reduction in p21 and phospho-pRb levels in myeloma cells, whereas cyclin D1, cyclin D2, cyclin E, CDK4, CDK6, p16 and p27 remained unchanged." (PMID 23029529, 2012). "Cyclin D1 can also be expressed strongly in approximately one-quarter of plasma cell myeloma cases." (PMID 20350332, 2010).
myeloma (continued). "Also, butein has been extensively tested and has been shown to inhibit the expression of Bcl-xL, Bcl-2, cyclin D1, and Mcl-1 in multiple myeloma cell lines (U266), and the expression of cyclin D1, Bcl-2, Bcl-xL, survivin, and VEGF in a liver cancer cell line (HepG2)." (PMID 38539427, 2024). "Our results demonstrate that APG treatment significantly downregulated Cyclin D1 and CDK2 expression while upregulating P21 in multiple myeloma (MM) cells." (PMID 41020839, 2025). "Our data therefore indicate that cyclin D1 overexpression in KMS‐28BM and OPM2 myeloma cell lines leads to changes in cell morphology and reduces cell adhesion ability." (PMID 40674249, 2025). "Translocations bring different oncogenes (such as Cyclin D1 (CCND1), CCND3, fibroblast growth factor receptor 3 (FGFR3), multiple myeloma SET-domain (MMSET/WHSC1), MAF or MAFB) under the control of the IgH enhancer." (PMID 33916289, 2021). "Among the stable myeloma precursor condition cases, we identified only 11 SV hotspots: all translocations between the IGH locus and CCND1 (n = 7), MAFB (n = 2), CCND3 (n = 1), and LTBR|LAG3 (n = 1)." (PMID 33767199, 2021). "Distinct myeloma transcriptome profiles are primarily driven by myeloma initiating events (MIE) and converge into a mutually exclusive overexpression of the CCND1 and CCND2 oncogenes." (PMID 34521827, 2021). "We discovered that 5hmC strongly persists at key oncogenic genes such as CCND1, CCND2 and MMSET and characterized domains that are specifically hydroxymethylated in myeloma subgroups." (PMID 33138842, 2020). "Conversely, methylation-mediated silencing of miR-340-5p enhanced myeloma plasma cell proliferation via upregulation of CCND1 and MAPK signaling (NRAS/MEKK1/MEKKK3/p-ERK) in addition to enhancing myeloma cell survival by targeting XIAP." (PMID 31064412, 2019). "Activation of AMPK can induce G0/G1 phase cell cycle arrest by downregulating cyclin D1 in CRC and myeloma cells." (PMID 31887988, 2019). "We note that these patterns of gene expression associated with RAS-RAF mutations are capable of further subtyping molecular subgroups of myeloma, especially in the D1-HRD, D2, and CCND1-11q13 subgroups where significant gene expression patterns were observed." (PMID 28427158, 2017). "For example, the large intergenic region upstream of the human Cyclin D1 (CCND1) locus on 11q13 is a hotspot for chromosomal translocations, particularly in multiple myelomas." (PMID 25799187, 2015). "However, according to a previous study, cyclin D1 induces UPR and ER stress-mediated apoptosis in myeloma cells." (PMID 40305155, 2025). "Knockdown of SNHG16 in multiple myeloma cells suppressed cell proliferation, induced cell arrest and promoted the apoptosis via inducing cleaved-Caspase-3, cleaved-Caspase-9, Foxa3a and Bax expression, while inhibiting CCND1, Bcl-2, Cyclin D1, PI3K and p-AKT." (PMID 35740344, 2022). "Although we did not investigate the downstream targets of HDAC7 that may contribute to the decreased cell growth, HDAC7 regulates cyclin D1 expression in osteogenesis, and it is possible that this function of HDAC7 is conserved in myeloma." (PMID 34888496, 2021). "In addition, MRBE repressed the expression of the β-catenin/T-cell factor (TCF)-dependent genes, cmyc and cyclin D1, thus inhibiting the proliferation of RPMI-8226 multiple myeloma (MM) cells." (PMID 34584036, 2021). "The gains of CCND1 and IGH observed in PCN cases could be described as templated insertions, a previously reported complex event found in about 20% of plasma cell myeloma cases." (PMID 34124820, 2021).
myeloma (continued). "Multiple myeloma is an incurable plasma cell malignancy, which is characterized by recurrent chromosomal aberrations that drive the expression of established oncogenes such as MYC, Cyclin D1, FGFR3/MMSET and MAF/MAFB." (PMID 33494394, 2021). "Next, we determined the presence of neutral and acid sphingomyelinase mRNA as well as total secreted and cellular SMase in human multiple myeloma cell lines (HMCL) representing different genetic subtypes of MM, including JJN3 (c-Maf), LP1 (MMSET/FGFR3), OPM2 (MMSET/FGFR3), and U266 (CCND1)." (PMID 31756922, 2019). "Other examples of translocation between IGH and other oncogenes are BCL2 in FL, BCL6 in diffuse large B cell lymphoma (DLBCL) and CCND1 (Cyclin D1), CCND3 (Cyclin D3), FGFR3/MMSET (Fibroblast growth factor receptor 3/multiple myeloma SET domain), and MAF (c-maf) in multiple myeloma (MM)." (PMID 28867784, 2017). "The knockdown of STAT3 and suppression of PI3K each significantly decreased but did not completely abolish Reelin-mediated Cyclin D1 upreguation and myeloma cell proliferation." (PMID 28345605, 2017). "Cyclin D1 is not expressed in the B-cell lineage but is found in multiple myeloma (MM) cells in almost 50% of patients with this condition." (PMID 25881299, 2015). "The study findings convincingly showed that an up-regulation of p27 but not p21 and down-regulation of cyclin D1 were the most important and central event in celastrol-induced G1 arrest in human myeloma cells." (PMID 24755677, 2014). "Furthermore, our results seem to indicate that Dex had no pro-apoptotic effects on CCND1 myeloma cells both in vitro and in vivo, despite the presence of effective GR." (PMID 26323097, 2015). "In addition, cyclin D1 protein expression was 1.8-fold reduced upon co-cultivation with KMS12-PE myeloma cells whereas no change was seen on mRNA level (p = 0.0033)." (PMID 25886144, 2015). "Furthermore, a research group from the Mayo clinic (USA) identified kinetin riboside from a chemical library screen as the suppressor of cyclin D1 and D2 (CCND1 and CCND2) expression, showing that kinetin riboside could potentially act as a therapeutic agent for multiple myeloma." (PMID 20032881, 2009). "This heterogeneity converges, in most cases, to a functionally dichotomous, mutually exclusive overexpression of the cell cycle regulators CCND1 and CCND2 to which myeloma PC remain addicted, irrespective of primary or secondary genetic events." (PMID 34521827, 2021). "We validated this using two MAF-, two CCND1- and one MMSET-translocated myeloma cell lines as a test set not used in training the model, and confirmed separation of samples according to MIE in the LF2-LF3-LF5 MOFA space." (PMID 34521827, 2021). "Of note, CCND2 myeloma cells overexpress CDK6 and CDK4 while CCND1 myeloma cells overexpress CDK4 but not CDK6, suggesting that CDK4 is “empty” of cyclin D in CCND2 myeloma cells." (PMID 30545397, 2018). "In agreement with the gene model, compared with bortezomib-sensitive myeloma cell lines (negative control), there was an increase in mRNA expression of SCN9A, RGS7, NTF3, HSPB8, and ZBED1 and a decrease in CCND1, COBLL1, EGR1, OCLN, and ZBED1 mRNA expression of bortezomib-resistant cell lines." (PMID 36467498, 2022). "For example, in multiple myeloma cells, APRIL promotes cell cycle progression in cyclin D2-positive cells by upregulating CDK4, CDK6, and phospho-retinoblastoma protein, but did not regulated cell-cycle proteins in cyclin D1-positive cells." (PMID 25826583, 2015).
lymphoma (121 papers, 2001 to 2026). A malignant (clonal) proliferation of B- lymphocytes or T- lymphocytes which involves the lymph nodes, bone marrow and/or extranodal sites. "This case underscores the importance of comprehensive diagnostic evaluation in Cyclin D1-positive rectal masses, particularly when there is an atypical response to standard lymphoma regimens." (PMID 40821198, 2025). "For example, a mutation in the Cyclin D1 encoding CCND1 gene that is associated with rare lymphomas, creates a new pre-mature PAS, which, if used, removes most of its 3′UTR containing destabilization elements normally present in the CCND1 mRNA." (PMID 39321865, 2025). "The treatment with drug combination for 24 h caused a decrease of cyclin D1, and cyclin E in lymphoma cells, in parallel the level of p21 protein and p27 increased." (PMID 28315173, 2017). "The NF-κB family and signalling pathway promotes proliferation via regulation of genes such as cyclin D1, D3, has been linked to gastric, prostate and breast malignancies and has been studied extensively in lymphomas." (PMID 27906095, 2016). "As cyclin D1 is linked to a poor prognosis for patients, its expression may result in a misleading lymphoma diagnosis in cases of high-grade morphology." (PMID 36312606, 2022). "Although IGH/CCND1 rearrangement is the most crucial initial event, additional gene mutations or the addition of aberrant cytogenetic event are necessary to destabilize the indolent lymphoma." (PMID 29246179, 2017). "This is also associated with miRNA regulation, and it has been demonstrated that PRMT5 promotes lymphoma by increasing cyclin D1 and c-Myc expression through inhibition of miR-33b, miR-96, and miR-503." (PMID 41154773, 2025). "The transcription level of cyclin d3 (Ccnd3) was high, whereas the expression levels of cyclin d1 (Ccnd1) and d2 (Ccnd2) were quite low, presumably reflecting the characteristics of T lymphomas, such as Jurkat cells." (PMID 40734673, 2025). "In a Myc-induced lymphoma model, TTP was found to be downregulated and restoration of TTP in these tumors led to the decay of mRNAs of Fst1, a pro-inflammatory cytokine and CCND1 thereby impairing the development and maintenance of lymphomas." (PMID 38571491, 2024). "Herein, we report a case of HGBL with MYC, BCL2, BCL6, and CCND1 rearrangements, a so-called quadruple hit lymphoma and describe its molecular and cytogenetic features." (PMID 38914869, 2024). "In DLBCL, the data suggests that the CCND1 rearrangement is a secondary event during lymphoma evolution." (PMID 38914869, 2024). "C-myc has been shown to collaborate with cyclin D1, N-myc, or L-myc to induce lymphomas in transgenic mice." (PMID 36838737, 2023). "Once confirmation of a hematolymphoid origin is established with CD45, the ideal IHC lymphoma work up for DLBCL includes CD3, CD20, CD5, CD10, bcl-2, bcl-6, MUM1, cyclin D1, CD30, Ki-67, and Epstein-Barr virus-encoded RNA (EBER) ISH." (PMID 37958219, 2023). "For example, cyclin D1b, the oncogenic form of cyclin D1, expressed in lymphomas, results from alternative splicing." (PMID 35740961, 2022). "The aim of this study is to investigate the expression and frequency of cyclin D1 in HGBL and its association with double expressor and triple expressor lymphomas." (PMID 36312606, 2022). "Now, a few studies are being conducted at an international level, showing the expression of cyclin D1 in triple expressors, regarding them as "quadruple-hit lymphoma"." (PMID 36312606, 2022). "An example supporting this idea is that B cell–specific inactivation of ATM (one of the traits in our study) synergizes with ectopic cyclin D1 expression to promote pregerminal center lymphoma in mice." (PMID 34882582, 2022). "This study showed a very low frequency of cyclin D1 expression in double and triple expressor lymphomas." (PMID 36312606, 2022). "All samples used in this analysis are lymphomas and express CCND1 mRNA at a sufficient level to sustain lymphomagenesis." (PMID 35145272, 2022).